RN7SL239P (RNA, 7SL, cytoplasmic 239, pseudogene)
Gene: Miscellaneous RNA gene on chromosome 11 (74,845,910 to 74,846,209, forward strand). Ensembl gene ENSG00000242999.
Homologues: Orthologues: chimpanzee Metazoa_SRP (99% identical), macaque Metazoa_SRP (93% identical). Paralogues in human: RN7SL2 (83% identical), RN7SL1 (83% identical), RN7SL3 (83% identical), RN7SL672P (80% identical), RN7SL566P (80% identical), RN7SL296P (79% identical), RN7SL543P (79% identical), RN7SL278P (79% identical), RN7SL492P (79% identical), RN7SL732P (79% identical), RN7SL127P (79% identical), RN7SL329P (79% identical), and 704 more.